EGFR (epidermal growth factor receptor)
Diseases named in the same sentence as EGFR in open-access papers (continued):
Sharing a sentence is not in itself a finding about the gene and the disease.
fungal infection (8 papers, 2018 to 2025). "Here, we show that in small-airway epithelial cells, the EGFR acts as a sensor for A. fumigatus that triggers the production of chemokines in response to fungal infection." (PMID 39475281, 2024). "Total proteins of VK2/E6E7 cells were extracted at 1, 2, 4, 6, 8 and 10 h post fungal infection for measurement of the activation of EGFR-MAPK pathway." (PMID 35720274, 2022). "Given that Mucorales fungi also activate EGFR signalling to induce fungal uptake into airway epithelial cells, collectively these studies demonstrate the critical importance of EGFR in fungal infections." (PMID 31288097, 2019). "A limitation of all studies of the role of EGFR in fungal infections in mice is that they have relied on small molecule inhibitors of EGFR such as gefitinib, which might have off-target effects." (PMID 39314401, 2024). "A limitation of all studies of the role of EGFR in fungal infections in mice is that they have relied on small molecule inhibitors of EGFR such as gefitinib (9, –, 11, 31), which might have off-target effects." (PMID 39475281, 2024). "However, it is probable that mice with conditional, site specific disruption of EGFR could be developed and used to test the role of this receptor in the pathogenesis of fungal infections." (PMID 39314401, 2024). "Inhibition of EGFR signaling with cetuximab or gefitinib, which are both FDA-approved inhibitors of EGFR, leads to a reduction in invasion and damage during fungal infection, and gefitinib prolonged survival in a mouse model." (PMID 33926528, 2021).
GEJ adenocarcinoma (8 papers, 2009 to 2025). "Currently, HER-2 and EGFR are few known molecules whose therapeutic effects for GEJ adenocarcinoma have been established in clinical trial." (PMID 24236193, 2013). "EGFR inhibitors have shown modest clinical activity, primarily in patients with esophageal and gastroesophageal junction adenocarcinomas." (PMID 19636422, 2009). "Our data also support the notion that PAK1 is an important node in the PAK1/HER-2/EGFR network and may be a targetable molecule for GEJ adenocarcinoma." (PMID 24236193, 2013). "Thus, therapeutic strategy targeting PAK1/HER-2/EGFR network holds promise for the treatment of GEJ adenocarcinoma." (PMID 24236193, 2013). "We performed this meta-analysis of randomized trials to evaluate whether the addition of an anti-EGFR agent to chemotherapy can produce survival benefits in patients with advanced EAC, GAC, or gastroesophageal junction adenocarcinoma (GEJAC)." (PMID 29228748, 2017). "Our results show that EGFR status is not prognostic of patient outcome in metastatic gastric and GE junction adenocarcinoma." (PMID 23153332, 2012).
glaucoma (8 papers, 2008 to 2025). Increased pressure in the eyeball due to obstruction of the outflow of aqueous humor. "Treatment with EGFR inhibitors has been reported as neuroprotective in rat models of glaucoma and spinal cord injury by acting preferentially on reactive astrocytes." (PMID 38977310, 2024). "As an example, pilocarpine 72 is used for the treatment of xerostomia and glaucoma, topsentin 73 shows anticancer activity and isonaamine A 74 also shows anticancer activity through its action as an inhibitor of the epidermal growth factor receptor (EGFR)." (PMID 36677894, 2023). "This study suggested that C3 may play a beneficial role during the early stages of glaucoma, possibly through activation of the epidermal growth factor receptor (EGFR) signaling pathway in ONH astrocytes." (PMID 38396986, 2024). "EGFR inhibitor AG1478 substantially increased the number of eyes with moderate or severe glaucoma." (PMID 36466782, 2022). "EGFR activation is characteristic of reactive astrocytes and has been shown in glaucoma." (PMID 18822132, 2008).
hemangiosarcoma (8 papers, 2017 to 2025). "The importance of EGFR was suggested in a study of a cell line derived from a radiation-associated angiosarcoma where inhibition of the VEGFR2/EGFR/RET axis resulted in decreased cell proliferation." (PMID 29515789, 2018). "• Expression higher in serum of dogs with splenic hemangiosarcoma• Increasing EGFR and Akt signaling• EGFR supports anchorage-independent growth and metastasis in canine hemangiosarcoma." (PMID 38826780, 2024). "Phosphatidylinositol‐4,5‐bisphosphate 3‐kinase catalytic subunit alpha (PIK3CA) is associated with hemangiosarcoma (HSA) and is phosphorylated by AKT, which enhances epidermal growth factor receptor (EGFR) signaling." (PMID 36349142, 2022). "A similar study of canine hemangiosarcoma, which express both EGFR and uPAR, showed that EGFATFKDEL effectively killed both hemangiosarcoma cells in monolayer as well as hemangiospheres enriched for cancer stem cells at subnanamolar doses over 72 hours." (PMID 29552283, 2018).
Ménétrier’s disease (8 papers, 2019 to 2025). "Overexpression of TGFA causes an alteration of gastric lineage cell commitment towards pit cells, and aberrant TGFA/EGFR signaling is also associated with the development of a rare hypertrophic disorder, Ménétrier’s disease, characterized by massive foveolar hyperplasia." (PMID 41365858, 2025). "Taken together, Rab25 loss can promote pit cell commitment by enhancing TGFA secretion in gastric epithelial cells, and excessive TGFA secretion due to loss of Rab25 can cause EGFR activation and lead to a stomach phenotype resembling human Ménétrier’s disease." (PMID 41365858, 2025). "Our enrichment analysis showing downregulation of EGFR signaling during parietal cell differentiation in healthy gastric glands may explain the loss of parietal cell phenotypes in Ménétrier’s disease patients, where TGFα is overexpressed." (PMID 37386010, 2023). "In a previous clinical report, antibody neutralization of EGFR in a patient with Ménétrier’s disease ameliorated disease severity." (PMID 41365858, 2025). "Ménétrier’s disease is a rare gastric lesion characterized by upregulation of TGFA/EGFR, giant rugal folds, and massive foveolar hyperplasia." (PMID 41365858, 2025). "Upregulated expressions of transforming growth factor alpha (TGF-α) and epidermal growth factor receptor (EGFR) in the gastric mucosa of individuals diagnosed with Ménétrier’s disease have been demonstrated." (PMID 31123980, 2019). "Indeed, blockade of EGFR ameliorated Ménétrier’s disease along with reduction of foveolar hyperplasia." (PMID 41365858, 2025). "Importantly, treatment of Ménétrier’s disease patients with antibodies against the EGFR led to amelioration of the foveolar hyperplasia, with decreases in phosphorylation of EGFR and ERK1/2, as well as return of gastric parietal cells." (PMID 30585163, 2019). "Also, EW disrupts TGFα- EGFR pathway by increasing signaling, which in transgenic animals and Mènètrier’s disease reduces ZC and PC number, respectively." (PMID 31892140, 2019). "Thus, the Ménétrier’s disease scenario is consistent with selective activation of foveolar hyperplasia through stimulation of EGFR and activation of the Ras/ERK pathway." (PMID 30585163, 2019). "While Ménétrier’s disease is rare in humans, the molecular mechanisms involving TGF-α/EGFR signaling and foveolar hyperplasia provide insights into growth factor-driven gastric pathology." (PMID 40673273, 2025).
periodontitis (8 papers, 2017 to 2026). An acute or chronic inflammatory process that affects the tissues that surround and support the teeth. "In summary, our findings demonstrate that EPO‐EVs, highly enriched with miR‐5107‐5p, partially mitigate inflammatory bone loss in periodontitis through the EGFR/RhoA axis, suggesting a potential therapeutic target for periodontitis treatment." (PMID 40289904, 2025). "The abundant miR‐5107‐5p in EVs, following EPO stimulation, alleviates inflammatory bone loss in periodontitis mouse models through the EGFR/RhoA axis." (PMID 40289904, 2025). "The data demonstrate that the addition of mimic‐5107 or EPO‐EVs effectively targets EGFR and further enhances RhoA activity, thereby alleviating inflammatory bone loss in LPS‐induced mBMSCs and promoting alveolar bone development in periodontitis mouse models." (PMID 40289904, 2025). "On the other hand, recent studies showed that inhibition of EGFR reduced the severity of bone loss and the inflammatory response in an experimental mouse ligature model of periodontitis." (PMID 35491845, 2022). "We found that the expression of HO-1 was regulated by EGFR silencing, and the inhibitory effects of periodontitis and alveolar bone loss were reversed." (PMID 33917440, 2021). "Therefore, to confirm the role of EGFR in the inhibition of periodontitis and alveolar bone loss following induction of HO-1 expression by ginsenosides, EGFR was silencing with EGFR siRNA." (PMID 33917440, 2021). "In addition, in an in vitro model of PG-LPS-induced periodontitis, major ginsenosides demonstrated the effect of controlling EGFR-mediated HO-1 on the inhibitory effect of periodontal inflammation and alveolar bone loss, an important treatment strategy for periodontitis." (PMID 33917440, 2021). "Overall, EVs from EPO pretreated macrophages restore the osteogenic capacity of mBMSCs under inflammation by inhibiting EGFR expression, providing new insight into therapeutic mechanisms and offering a promising approach for future periodontitis treatment." (PMID 40289904, 2025). "Together, these findings argue that permanent stimulation of EGFR may be harmful for patients with periodontitis." (PMID 35491845, 2022). "PD153035, an epidermal growth factor receptor (EGFR) inhibitor, was evaluated in a periodontitis mouse model." (PMID 41484074, 2026). "However, the role of EGFR-mediated HO-1 in the induction of periodontitis in HPDL cells stimulated with PG-LPS has not yet been investigated." (PMID 33917440, 2021). "However, a role for HO-1 and EGFR in human periodontal ligament cells, in which periodontitis is induced, has not been identified." (PMID 33917440, 2021). "To investigate whether miR‐5107‐5p suppresses EGFR expression and contributes to EPO‐EVs‐mediated bone regeneration under inflammatory conditions in vivo, we employed Antagomir‐5107 as miR‐5107‐5p specific inhibitor in the periodontitis mice model every 3 days after ligature removal." (PMID 40289904, 2025). "However, the role of EGFR in the regulation of HO-1 expression in HPDL cells and periodontitis has not been confirmed." (PMID 33917440, 2021).
salivary gland tumors (8 papers, 2008 to 2025). "Of note, the same study demonstrated a clinical benefit from this drug in a patient with an EGFR L858R-mutated salivary gland tumor." (PMID 38612902, 2024). "The objectives of the present study were to evaluate the detection sensitivity of GNPs-EGFR in a subset of human salivary gland tumors for discriminating benign from malignant tumors with histopathology as a gold standard." (PMID 40095737, 2025). "An increased number of reports have been published in recent years on the expression of epidermal growth factor receptor in salivary gland tumors due to the potential for treatment with targeted therapy, particularly in aggressive salivary duct carcinomas." (PMID 40095737, 2025). "One of the aims of our study was to investigate expression of EGFR in different subtypes of salivary gland tumours." (PMID 28377929, 2017). "Epidermal growth factor receptor (EGFR), an important therapeutic target and target of certain miRNAs (i.e., miR-133b), shows variable degrees of expression in salivary gland tumours." (PMID 28377929, 2017). "Several experiments performed were describing expression of EGFR in salivary gland tumours, however, with variable degrees of expression being reported so far, from 17% to 100% of cases, depending on histological subtypes." (PMID 28377929, 2017). "Accordingly, our results showed statistically significant higher percentage of EGFR reactive samples (58%) among patients that died due to the presence of salivary gland tumours compared to those that were still alive (30%) at the time of analysis." (PMID 28377929, 2017). "Although many studies on the role of EGFR in salivary gland tumors have been reported, there is some debate about its prognostic significance." (PMID 23231994, 2012). "To date, only a few, small clinical trials have investigated the antitumor activity of anti-EGFR targeted agents in the salivary gland neoplasms." (PMID 18826647, 2008). "However, EGFR alterations are generally rare in salivary gland tumors overall and were barely noted in our dataset." (PMID 36831055, 2023). "In 27 of 70 salivary gland tumours we found positive reactivity (3+ IHC staining) of EGFR." (PMID 28377929, 2017). "In demonstrated absence of EGFR gene mutations in malignant salivary gland tumours, we can conclude that variability in EGFR expression occurs as a consequence of gene amplification and chromosome 7 polysomy." (PMID 28377929, 2017). "In salivary gland tumours we have not found any nucleotide changes being responsible for activation of EGFR and its elevated expression pattern." (PMID 28377929, 2017).
serous carcinoma (8 papers, 2011 to 2025). "We report a case series of three women with advanced-stage low-grade serous carcinoma harboring RAS mutation who had stabilization of their disease during several months under targeted therapy combining anti-EGFR antibody and MEK inhibitor." (PMID 35328764, 2022).
thymic carcinoma (8 papers, 2013 to 2025). Thymic carcinoma (TC) is a type of thymic epithelial neoplasm characterized by a high malignant potential. "Paraffin-embedded sections of the thymic carcinoma were then analyzed for the 18–21 mutation of the EGFR gene." (PMID 25789028, 2015). "Activating EGFR mutations seem to be exceptionally rare in thymic carcinomas with only few reported EGFR missense mutations in exon 21 (p.L858R in two cases and p.G863D in one case)." (PMID 24934485, 2014). "Therefore, it was concluded that the EGFR exon 21 L858R mutation in the thymic carcinoma tissue was likely to be a false-positive ARMS result." (PMID 25789028, 2015). "Of recent interest are new targeted therapies such as Tarceva® (erlotinib), an epidermal growth factor receptor (EGFR) inhibitor, for treatment of recurrent thymic carcinoma." (PMID 29147359, 2013). "Notably, a significant proportion (86%) of thymic carcinomas display moderate to high levels of IGF-1R expression, which is closely associated with epidermal growth factor receptor (EGFR) overexpression." (PMID 37849766, 2023). "In the present study, an L858R mutation in exon 21 of the EGFR gene was identified in the tissue of the thymic carcinoma, but the patient did not respond to treatment with TKIs." (PMID 25789028, 2015).
thyroid tumor (8 papers, 2013 to 2025). A benign or malignant neoplasm affecting the thyroid gland. "After empirical chemotherapy for CUP, an NGS-based multiplex assay performed using a resected specimen of thyroid tumor detected the EGFR mutation c.2573 T > G p.Leu858Arg (L858R)." (PMID 33267781, 2020). "In this work, we are investigating the expression of EGFR and its regulation by miR-7-5p and miR-146b-5p in PTC and NIFTP as models of high risk and low risk thyroid tumors respectively." (PMID 37114127, 2023). "MiR-7-5p, IRS2 and EGFR expressions are correlated with the aggressivity of thyroid tumors: more aggressive BRAFV600E positive PTC exhibit a more pronounced decrease of miR-7-5p expression and increase of IRS2 or EGFR expressions compared to BRAFV600E negative PTC." (PMID 34381564, 2021). "Moreover, MAPK/ERK, EGFR/ERBB and PI3K/AKT, widely recognized as the main deregulated signaling pathways in thyroid tumors, have CDK4/6 as major integrating node." (PMID 37964967, 2023).
allergic asthma (7 papers, 2017 to 2025). A asthma with a basis in a pathological type I hypersensitivity reaction. "Mucous metaplasia and airway remodeling as hallmarks of allergic asthma have been associated with expression and activation of epidermal growth factor receptor (EGFR) signaling." (PMID 29257052, 2017). "Heijink and colleagues observed that EGFR phosphorylation and activation following E-cadherin silencing drives EGFR-dependent recruitment of Th2 cells in allergic asthma, through the induction of TARC/CCL2, a Th2-attracting molecule." (PMID 40007608, 2025). "In allergic asthma, activation and expression of epidermal growth factor receptor (EGFR) signaling are signs of mucous metaplasia and airway remodelling." (PMID 35796922, 2022). "In HDM-induced allergic asthma mouse models, oxidative EGFR activation was diminished by treatment with DUOX1 inhibitor with improvement of airway inflammation including neutrophilic airway inflammation and Th2 cytokine production and mucus metaplasia." (PMID 33217964, 2020). "In a in vivo experiment using the house dust mite (HDM)-induced allergic asthma mice model, expression of EGFR increased after HDM inhalation, which was inhibited by treatment with EGFR inhibitor, erlotinib." (PMID 33217964, 2020). "The EGFR-GM-CSF axis might be a potential therapeutic target for allergic asthma." (PMID 33217964, 2020).
anal squamous cell carcinoma (7 papers, 2010 to 2022). A squamous cell carcinoma (SCC) arising from the anal canal or the anal margin (perianal skin). "Anti-EGFR therapy appears to be a potential treatment option for squamous cell anal carcinoma (SCAC)." (PMID 24642661, 2014). "Squamous cell carcinoma of the anus, in common with cervical and head and neck squamous tumours, regularly overexpresses the epidermal growth factor receptor (EGFR)." (PMID 22619735, 2012). "In the present study we showed immunohistochemical evidence of EGFR expression (i.e., at least 5% of tumour cells were positive) in 83.7% interpretable cases of squamous cell carcinoma of the anus." (PMID 20459770, 2010). "Epidermal growth factor receptor (EGFR) is usually expressed in squamous cell anal carcinoma (SCAC) and anti-EGFR agents could represent a valid treatment strategy, also considering that KRAS and BRAF mutations are rare events in this type of cancer." (PMID 27886225, 2016). "Thus, an important conclusion of this analysis is that further formal analysis of anti-EGFR therapy is merited for anal squamous cell carcinomas." (PMID 26498363, 2015). "EGFR mutations were absent from squamous cell carcinoma of the anus and tonsils, but EGFR protein expression was detected in the majority of the cases." (PMID 20459770, 2010). "Currently, few data regarding EGFR expression in squamous cell carcinoma of the anus are available." (PMID 20459770, 2010). "Moreover, cetuximab may be an effective treatment for anal squamous cell carcinoma because EGFR is overexpressed in many cases, while KRAS, NRAS, and BRAF mutations are not observed in most cases." (PMID 35723765, 2022). "In a study of 95 tumour biopsies from squamous cell anal cancers, the tumours lacked the common KRAS and EGFR mutations." (PMID 22619735, 2012). "There are no approved targeted treatment options for patients with anal squamous cell carcinoma, although there are multiple anecdotal reports demonstrating the therapeutic benefit of the anti-EGFR monoclonal antibody cetuximab in the metastatic setting in chemotherapy-refractory cases." (PMID 26498363, 2015).